BCL11B (BCL11 transcription factor B)
Description:
Key regulator of both differentiation and survival of T-lymphocytes during thymocyte development in mammals. Essential in controlling the responsiveness of hematopoietic stem cells to chemotactic signals by modulating the expression of the receptors CCR7 and CCR9, which direct the movement of progenitor cells from the bone marrow to the thymus. Is a regulator of IL2 promoter and enhances IL2 expression in activated CD4(+) T-lymphocytes. Tumor-suppressor that represses transcription through direct, TFCOUP2-independent binding to a GC-rich response element (By similarity).
Synonyms: CTIP2; RIT1; CTIP-2; hRIT1-alpha; SMARCM2; ATL1; ATL1-alpha; ATL1-beta; ATL1-delta; ATL1-gamma; IDDFSTA; IMD49; ZNF856B
Tractability: PROTAC: UniProt records ubiquitination sites on it; ubiquitination databases record sites on it; its protein half-life has been measured.
Gene: Protein-coding gene on chromosome 14 (99,169,287 to 99,272,197, reverse strand). Ensembl gene ENSG00000127152.
Subcellular location: Nucleus
Subcellular location (Human Protein Atlas): Nucleoplasm; Nucleoli fibrillar center
Pathways (Reactome):
Chromatin organization: Formation of neuronal progenitor and neuronal BAF (npBAF and nBAF); Formation of the embryonic stem cell BAF (esBAF) complex
Gene Ontology:
Molecular function: protein binding; sequence-specific double-stranded DNA binding; DNA-binding transcription factor activity; RNA polymerase II cis-regulatory region sequence-specific DNA binding; DNA-binding transcription activator activity, RNA polymerase II-specific; sequence-specific DNA binding
Biological process: hematopoietic stem cell migration; lymphoid lineage cell migration into thymus; positive regulation of transcription by RNA polymerase II; regulation of transcription by RNA polymerase II
Cellular component: SWI/SNF complex; nucleoplasm; nucleus; neuron projection
Genetic constraint (gnomAD): Loss-of-function variants: 10 observed, 36.73 expected, observed/expected ratio (o/e) 0.27, 90% interval 0.17 to 0.46. The synonymous counts are far from expectation, so gnomAD's model fits this gene poorly and the ratio says little. Missense variants: 979 observed, 1,096.2 expected, observed/expected ratio (o/e) 0.89, 90% interval 0.85 to 0.94. Synonymous variants: 724 observed, 548.02 expected, observed/expected ratio (o/e) 1.32, 90% interval 1.24 to 1.4.
Gene-disease validity (ClinGen):
ClinGen rates the evidence that BCL11B causes each of these diseases.
intellectual developmental disorder with speech delay, dysmorphic facies, and t-cell abnormalities (autosomal dominant): Definitive. Any BAFopathy in which the cause of the disease is a mutation in the BCL11B gene.
Homologues: Orthologues: chimpanzee BCL11B (99% identical), macaque BCL11B (99% identical), dog BCL11B (98% identical), pig BCL11B (98% identical), guinea pig BCL11B (97% identical), mouse Bcl11b (93% identical), rat Bcl11b (91% identical), tropical clawed frog BCL11B (71% identical), zebrafish bcl11ba (12% identical). Paralogues in human: BCL11A (59% identical), SALL3 (17% identical), HIVEP3 (17% identical), SALL1 (17% identical), HIVEP1 (16% identical), HIVEP2 (15% identical), SALL4 (15% identical), ZNF536 (14% identical), RREB1 (13% identical), SALL2 (11% identical), ZNF217 (10% identical), ZNF516 (10% identical), and 2 more.
Diseases named in the same sentence as BCL11B in open-access papers:
BCL11B is named in the same sentence as 143 diseases in open-access papers, as found by Europe PMC text mining. Sharing a sentence is not in itself a finding about the gene and the disease. The quoted sentences say what the papers report.
acute lymphoblastic leukemia (25 papers, 2007 to 2025). Leukemia with an acute onset, characterized by the presence of lymphoblasts in the bone marrow and the peripheral blood. "BCL11B (down regulated 12-fold) is a tumor suppressor that is widely mutated in acute lymphocytic leukemia and has recently been shown to be methylated, and thus likely down-regulated, in prostate cancers." (PMID 26847345, 2016). "Low expression of BCL11B has been associated with poor prognosis in T-acute lymphoblastic leukemia." (PMID 36376973, 2022). "By contrast, BCL11B haploinsufficiency is associated with T-cell Acute Lymphoblastic Leukemia (T-ALL) and neurological disorders." (PMID 38472338, 2024). "It has been reported that approximately 10% to 16% of T cell acute lymphoblastic leukemia (T-ALL) cases carry mutations altering the DNA-binding properties of BCL11B." (PMID 33807484, 2021). "Moreover, 80% of BCL11B-rearranged early T-cell precursor acute lymphoblastic leukemia (ALL) cases have activating FLT3 mutations." (PMID 38132393, 2023). "The bi‐directional role of BCL11B becomes relevant in the context of T cell acute lymphoblastic leukemia (T‐ALL)." (PMID 39976228, 2025). "In B cells, PRDM16 and DNMT3A for AML, PDCD1LG2 for Hodgkin’s lymphoma, LMNA for spritzed tumor, and BCL11B for T-cell acute lymphoblastic leukemia (T-ALL) harbored DMPs for HIV infection." (PMID 38466776, 2024). "Mice, bearing human oncogenes TAL BHLH Transcription Factor 1 (TAL1; SCL) or LIM Domain Only 1 (LMO1), responsible for T-cell acute lymphoblastic leukemia (T-ALL) development, were crossed with BCL11B floxed and with CRE-ER/lox mice." (PMID 35563322, 2022). "A chromosomal translocation between an upstream HOXA13 region and a downstream region of the BCL11B/CTIP2 locus has been described in T-cell acute lymphoblastic leukemia (T-ALL), resulting in a HOXA13 gene hyper-expression." (PMID 31137568, 2019). "We studied the impact of B-cell CLL/lymphoma 11b (BCL11b), a key regulator in normal T-cell development, in T-ALL patients enrolled into the German Multicenter Acute Lymphoblastic Leukemia Study Group trials (GMALL; n = 169)." (PMID 25023966, 2014). "Downregulation of the B-cell chronic lymphocytic leukemia (CLL)/lymphoma11B (BCL11B) gene by small interfering RNA (siRNA) leads to growth inhibition and apoptosis of the human T-cell acute lymphoblastic leukemia (T-ALL) cell line Molt-4." (PMID 21575156, 2011). "Previous studies showed that the inhibition of BCL11B expression by siRNA selectively inhibited proliferation and effectively induced apoptosis in human T-cell acute lymphoblastic leukemia (T-ALL) cell lines (Jurkat, Molt-4)." (PMID 21080944, 2010). "Previous study showed that downregulated BCL11B expression in T cell acute lymphoblastic leukemia (T-ALL) cell line Molt-4 inhibited cell proliferation and induce apoptosis, which may be related to PHTF1 gene overexpression." (PMID 26448723, 2015). "Bcl11b is a transcription factor important for T cell development and also a tumor-suppressor gene that is hemizygously inactivated in ~10% human T cell acute lymphoblastic leukemia (T-ALL) and several murine T-ALL models, including ATM(-/-) thymic lymphomas." (PMID 26219558, 2015). "BCL11B has also been studied in the context of malignancies, where it has been described as a haploinsufficient tumor suppressor in T-cell acute lymphoblastic leukemia (T-ALL)." (PMID 23527175, 2013). "In the immune system, BCL11B is expressed exclusively in the T cells and is involved in both translocations and inversions in human T-cell acute lymphoblastic leukemia (T-ALL)." (PMID 17941976, 2007).
leukemia (23 papers, 2007 to 2026). A malignant (clonal) hematologic disorder, involving hematopoietic stem cells and characterized by the presence of primitive or atypical myeloid or lymphoid cells in the bone marrow and the blood. "A dysregulation in BCL11B expression and genetic aberrations involving the BCL11B gene are associated with a plethora of pathologies, such as leukemia, cancer, and neurodegenerative disorders." (PMID 39976228, 2025). "Twelve Sca1‐Lmo2 leukemias were analyzed and revealed copy number loss of Cdkn2a/b (2/12) and Bcl11b (4/12), similar to human T‐ALL, as well as c‐Myc amplification (8/12)." (PMID 29880602, 2018). "Some of the PPP3CA interactor proteins implicated in leukemia pathobiology such as BCL11b, NPM1, GSK3β and Rb were further validated in Jurkat T-ALL cells expressing constitutively active PPP3CA*." (PMID 27304189, 2016). "BCL11B has been reported to be overexpressed in childhood leukemias, due to enhancer amplifications 3′ of the gene." (PMID 39853740, 2026). "These leukemias exhibit a distinct expression profile compared with other acute leukemia subtypes, and most rearrangements juxtapose BCL11B to super-enhancers, resulting in BCL11B overexpression that serves as a biomarker at diagnosis." (PMID 41374977, 2025). "Consistent with the genetic features, BCL11B was expressed in a small minority of cells (406 cells, 0.76%) in the common leukemia cluster and in <3% of cells in any individual patient." (PMID 39294124, 2024). "Because all these alterations invariably cause the transcriptional activation of the BCL11B gene, this leukemia subtype was called “BCL11B activated” AL (BCL11B-a AL)." (PMID 35454781, 2022). "This immature form of leukemia is driven by transcriptional activation of BCL11B, due to chromosomal rearrangements that juxtapose BCL11B to diverse, active super-enhancers, or to the ZEB2 gene, generating a ZEB2-BCL11B fusion." (PMID 34440292, 2021). "Surprisingly, in contrast to its tumor suppressive function in leukemia and lymphoma, we now show that BCL11B positively contributes to the transformed phenotype in Ewing sarcoma." (PMID 23527175, 2013). "This oncogenic capacity is in stark contrast to its tumor inhibitory function in leukemia and lymphoma – the cancers in which BCL11B have mainly been studied." (PMID 23527175, 2013). "Conversely, a BCL11B enhancer can also activate TLX3 in pediatric leukemia." (PMID 39853740, 2026). "Furthermore, it was shown that enhancer hijacking drives oncogenic BCL11B expression in lineage-ambiguous stem cell leukemia with expression of myeloid and T lymphoid markers." (PMID 39295773, 2024). "Although our results have to be validated in a larger patient cohort, BCL11B could be considered as a potential biomarker for this leukemia." (PMID 36376973, 2022). "Interestingly, several proteins implicated in leukemia pathobiology emerged amongst the novel PPP3CA interactors such as NPM1, BCL11b, GSK3β and KDM1 (also known as LSD1)." (PMID 27304189, 2016). "Importantly, several proteins implicated in leukemia pathobiology emerged amongst the novel PPP3CA interactors such as Rb, NPM1, BCL11b, GSK3β and KDM1 (also known as LSD1)." (PMID 27304189, 2016). "Whether or not loss/alternative functions of BCL11B are involved in leukaemia initiation/progression specifically in these patients remains unknown." (PMID 25565005, 2015). "The BCL11B/Rit1/CTIP2 gene was first identified in human chromosome 14q32.2, as a homologue to BCL11A/CTIP1, which is known to be involved in translocations in human leukemia." (PMID 17941976, 2007).
lymphoma (19 papers, 2007 to 2025). A malignant (clonal) proliferation of B- lymphocytes or T- lymphocytes which involves the lymph nodes, bone marrow and/or extranodal sites. "The region on mouse chromosome 12 where Bcl11b is located exhibits frequent allelic loss in murine lymphomas." (PMID 23383087, 2013). "Mouse lymphomas induced by 1,3-butadiene or 2',3'-dideoxycytidine were analysed for mutations in the Bcl11b gene using single strand conformation analysis and direct DNA sequencing." (PMID 17941976, 2007). "The role of Bcl11b in lymphomagenesis is also indicated by studies showing Bcl11b mutations in radiation-induced mouse lymphomas as well as inversions and translocations involving Bcl11b in human T-ALL." (PMID 17941976, 2007). "The region on mouse chromosome 12 where Bcl11b is located has previously shown frequent allelic loss in murine lymphomas." (PMID 17941976, 2007). "Forty-seven chemically induced lymphomas were analysed for mutations in the Bcl11b gene by SSCA and MegaBACE sequencing." (PMID 17941976, 2007). "In this study, we aimed to elucidate whether Bcl11b is mutated in lymphomas with allelic loss, and whether the mutations we detected conferred any effect on cell proliferation and apoptosis." (PMID 17941976, 2007). "B‐Cell CLL/Lymphoma 11B (BCL11B) is a C2H2 zinc finger transcription factor that has broad biological functions and is essential for the development of the immune system, neural system, cardiovascular system, dermis, and dentition." (PMID 36683525, 2023). "The mouse model of inducible BCL11B knockout we generated can be used to study the role of this gene in cancer development and the potential therapeutic effect of BCL11B inhibition in T-cell leukemia and lymphoma." (PMID 35563322, 2022). "To study its role in the development of T-cell neoplasms, we generated an inducible BCL11B knockout in a murine T cell leukemia/lymphoma model." (PMID 35563322, 2022). "Previous miRNAome analysis showed gga-miR-219b was significantly downregulated in MDV-induced lymphoma, and one of its potential target genes, B-cell chronic lymphocytic /lymphoma 11B (BCL11B) was predicted." (PMID 28652615, 2017). "In ATM−/− mice heterozygous loss of BCL11B reduced lethal thymic lymphoma by suppressing lymphoma progression but not initiation." (PMID 39295773, 2024). "BCL11B regulates thymocyte development and is a cancer suppressor gene in T-cell leukemia/lymphoma." (PMID 36600891, 2022). "Clonal expansion of cells with LOH at the Bcl11b locus has been reported as being one of the earliest detectable changes (along with Myc amplification) in the thymus post-irradiation but prior to the onset of lymphoma." (PMID 26125582, 2015). "However, BCL11B overexpression was found in the acute type of adult T-cell leukemia/lymphoma and the majority of T-ALL cell lines." (PMID 25644173, 2015).
lymphoma (continued). "Here we report that heterozygous loss of Bcl11b (Bcl11b(+/-)) unexpectedly reduced lethal thymic lymphoma in ATM(-/-) mice by suppressing lymphoma progression, but not initiation." (PMID 26219558, 2015). "Furthermore, deletions within BCL11B were found in irradiation-induced lymphomas in mice, suggesting that BCL11B is a haploinsufficient tumor suppressor." (PMID 25644173, 2015). "The suppression was associated with a T cell-mediated immune response in ATM(-/-)Bcl11b(+/-) mice, revealing a haploid insufficient function of Bcl11b in immune modulation against lymphoma and offering an explanation for the complex relationship between Bcl11b status with T-ALL prognosis." (PMID 26219558, 2015). "Moreover, amplifications of the BCL11B locus accompanied by increased mRNA expression and protein were shown in adult T cell leukemia/lymphoma and correlated with the aggressiveness of the disease which indicates a function opposite to tumor suppression." (PMID 20824091, 2010). "In humans overexpression of BCL11B has been linked to lymphoproliferative disorders like the T-cell acute lymphoblastic leukemia (T-ALL) and an acute form of adult T-cell leukemia/lymphoma." (PMID 20824091, 2010). "These authors identified similar but not identical mutations in the Bcl11b gene in radiation-induced mouse lymphomas." (PMID 17941976, 2007). "Therefore, BCL11B might be an attractive target for the specific therapy of T cell leukemia and lymphomas." (PMID 35563322, 2022). "Finally, intersecting specific DMGs of the two patients, we observed common tumor pathways involved in lymphoma and breast cancer including transcription factors and oncogenes (e.g., FOXD3/ESR1/HOXA9/BCL11B)." (PMID 37029309, 2023).
T-cell acute lymphoblastic leukemia (15 papers, 2009 to 2025). Acute lymphoblastic leukemia of T-cell origin. "Increased levels of BCL11B expression have been linked to human T-cell acute lymphoblastic leukemia, and the inhibition of BCL11B expression results in the apoptosis of malignant T-cells." (PMID 23383087, 2013). "BCL11B plays a crucial role in T-cell development and has been implicated in human T-cell acute lymphoblastic leukemia." (PMID 23383087, 2013). "The fusion genes BCL11B-TLX3, BCL11B-NKX2-5, BCL11B-TRD, and IKZF2-BCL11B have all been reported in T-cell acute lymphoblastic leukemia." (PMID 26186352, 2015). "In this chromosome locus, BCL11B may act as a tumor-suppressor gene in T-cell acute lymphoblastic leukemia." (PMID 24422944, 2013).
Huntington disease (14 papers, 2012 to 2025). Huntington disease (HD) is a rare neurodegenerative disorder of the central nervous system characterized by unwanted choreatic movements, behavioral and psychiatric disturbances and dementia. "Bcl11b (also known as Ctip2) is a zinc finger transcription factor that has been implicated in various disorders of the nervous system including Alzheimer’s and Huntington’s disease, and schizophrenia." (PMID 38358390, 2024). "Transcription factor BCL11B, which is expressed by all MSNs and deep layer cortical neurons, was recently proposed to drive selective neurodegeneration in Huntington’s disease and identified as a candidate risk gene in schizophrenia." (PMID 37519464, 2023). "BCL11B has been implicated in Alzheimer’s disease, Huntington’s disease, Neuro-HIV, learning, and memory, and its cellular role in cortical GABAergic neurons, medium spiny neurons, and vomeronasal sensory neurons have been studied." (PMID 37488168, 2023). "Bcl11b has been implicated in a number of disease states including Huntington's disease, Alzheimer's disease, HIV and T-Cell malignancy, amongst others." (PMID 28424591, 2017). "Besides its involvement in NDDs, BCL11B was previously linked to neurodegenerative diseases, such as Huntington’s disease, schizophrenia, Alzheimer’s disease, and amyotrophic lateral sclerosis (ALS), which indicates a role of BCL11B in the maintenance of functional neuronal connections." (PMID 38392344, 2024). "One of the “Pink” module gene transcripts with significant allelic and connectivity changes, Bcl11b, has been previously shown to strongly influence striatal gene expression and transcriptional dysregulation in Huntington’s disease." (PMID 23555609, 2013). "On the other hand, B-cell lymphoma/leukemia 11B (BCL11B) inhibits HIV transcription by recruiting a chromatin-modifying complex, and its disruption may cause Huntington’s disease and Alzheimer’s disease." (PMID 32970817, 2020). "Examining the adult and aging human as well as rodent brain suggests Bcl11b to be involved in a number of neurodegenerative disorders like Alzheimer’s disease (AD), Huntington’s disease (HD), schizophrenia, and amyotrophic lateral sclerosis (ALS)." (PMID 32322190, 2020). "In addition, BCL11B has been previously shown to be critical for neurodevelopmental transcription with implications in multiple diseases of the central nervous system such as Huntington’s disease and Alzheimer’s disease." (PMID 41159936, 2025).